NANOG (Nanog homeobox)
Diseases named in the same sentence as NANOG in open-access papers (continued):
Sharing a sentence is not in itself a finding about the gene and the disease.
tumor (continued). "However further experimental studies would be required in order to clarify the biological role of PGRMC1 in tumor stemness associated pathway, such as OCT3/SOX2/NANOG/KLF4." (PMID 34746100, 2021). "In addition, the abundances of circ_0072083, ALKBH5 and NANOG were evidently enhanced and miR-1252-5p expression was decreased in tumor tissues in U251/TR-sh-NC EXO + TMZ group, and these events were reversed in U251/TR-sh-circ_0072083 EXO + TMZ group." (PMID 33975615, 2021). "Nanog homeobox (NANOG) is a key stemness marker, which regulates tumor development." (PMID 33975615, 2021). "Moreover, NANOG is known for critically contributing to tumor initiation and epithelial–mesenchymal transition." (PMID 33439550, 2021). "Given the fundamental role of SOX2, OCT4, and NANOG in supporting self-renewal properties, we examined their levels in tumors that appeared early, demonstrating enhanced tumor-initiation ability, versus those that appeared late, showing poor tumor-initiation ability." (PMID 33445692, 2021). "Limiting dilution in in vivo experiments implicated SOX2, but not OCT4 or NANOG, with early tumor-initiation." (PMID 33445692, 2021). "Additionally, correlations between Tregs and CTLs infiltration and the expression of tumor PD-L1 and various well-established CSCs markers (i.e. NANOG, SOX2, OCT4, Nestin and PDPN) are also assessed." (PMID 34201050, 2021). "We found that OCT4-positive proliferating tumor cells simultaneously express NANOG." (PMID 34413299, 2021). "In addition, knockdown of TLR4 downregulated NFAT5, JMJD2B, and NANOG expression in the xenograft tumor tissues." (PMID 32684087, 2020). "Indeed, the localization of the fluorescence signal for NANOG colocalized with centrosomes in each of the nine examined tumor cell lines." (PMID 32168958, 2020). "Therefore, NANOG, an intrinsic factor of tumor cells, is a potential target to overcome the immune-refractoriness by re-invigorating the immune cycle of tumor-reactive T cells." (PMID 31992715, 2020). "In a previous report, we have demonstrated that hypoxic stress, by inducing the pluripotency factor NANOG in tumor cells, activates the expression and secretion of the tumor immunosuppressive TGF-β1 by a mechanism involving at least direct binding of NANOG to the TGF-β1 promoter." (PMID 33552076, 2020). "In addition, ALKBH5 promotes expression of NANOG, a well-known factor for the self-renewal process of undifferentiated ESCs, and thus it plays a role in primary tumor formation and metastasis." (PMID 31804607, 2020). "At the same time, the expression of NANOG, a tumour stem cell factor, increased." (PMID 32329191, 2020). "In addition, we have also found that NANOG confers multi-aggressive phenotypes to tumor cells through transcriptional induction of TCL1A and subsequent activation of the AKT-signaling pathway." (PMID 31992715, 2020). "In addition, DLBCL cell lines that overexpress HOXA9 and NANOG enhance tumor formation in a mouse model and enhance clonogenic ability in soft agar." (PMID 33288848, 2020). "Our results in nine tumor cell lines indicated that the centrosomal localization of NANOG might be common among tumor cells of various origins." (PMID 32168958, 2020). "Furthermore, western blotting confirmed that knockdown of NFAT5 suppressed ETBF stimulated-JMJD2B and NANOG expression in the xenograft tumor tissues, and the NANOG decrease was efficiently rescued by JMJD2B overexpression." (PMID 32684087, 2020). "Furthermore, expression of OCT4/NANOG in tumor cells is positively correlated with the amount of infiltrated immune cells within the tumor region." (PMID 33511137, 2020). "Moreover, Neu2-overexpressed tumor tissue samples showed reduction of pluripotent stem cells markers such as OCT4/SOX2/NANOG and PCS specific marker CD133 at the transcript level." (PMID 32575925, 2020). "Moreover, knockdown of JMJD2B blocked ETBF-induced NANOG upregulation in the xenograft tumor tissues." (PMID 32684087, 2020).
tumor (continued). "Genetic silencing of hypoxia-induced NANOG in tumor cells restored CTL-mediated tumor cell killing." (PMID 31540045, 2019). "Here we provide a proof of principle that chimeric NANOG repressor proteins, named NANEPs, could be used as anti-tumor molecules in a context-dependent manner." (PMID 30846719, 2019). "Our findings serve as a basis for forming new tumorigenic mechanism hypotheses and suggest that NANOG-mediated ICAM1 downregulation is a key factor allowing the formation of tumor tissue via the evasion of NK cell attack." (PMID 31619256, 2019). "Furthermore, NANOG is associated with maintenance of the stem-like phenotype of CSCs within the tumor, consistent with our observation of NANOG expression by some epithelial cells within the tumor." (PMID 31491003, 2019). "DCs loaded with NANOG peptides, a protein required for maintaining stem cell properties, could evoke a potent anti-tumor immune response against CSCs." (PMID 29971070, 2018). "In addition, CD133 depletion also suppresses tumor cell proliferation, colony formation, and the expression of stemness transcription factors including NANOG, OCT4, SOX2, and c-MYC." (PMID 29568348, 2018). "The significant difference in nuclear OCT4 and nucleocytoplasmic NANOG expressions between ccRCC, compared with the chRCC and pRCC tumor samples, indicates that OCT4 and NANOG may act as a diagnostic markers to distinguish ccRCC from chRCC and pRCC subtypes." (PMID 30082842, 2018). "Based on these findings, we suggest that there might be a positive involvement of OCT4/ NANOG, signaling pathways in tumor invasion and progression of RCC." (PMID 30082842, 2018). "This is consistent with the reduction of OCT4, NANOG and SOX2 expression, reduction in the BCSC population by loss of the ALDH1 and CD44+/CD24– population, the deformation of mammospheres, and the strong reduction in animal tumor volume and tumor weight." (PMID 30542507, 2018). "Suppression of NANOG inhibited self-renewal and tumor-forming capacity of the GSCs." (PMID 28611316, 2017). "The stemness markers SALL4 and NANOG were strongly expressed in tumor spheres." (PMID 28620148, 2017). "However, NANOG is highly expressed in both tumor tissue and peritumoral tissue, compared to normal tissue." (PMID 28626726, 2017). "Indeed, Terence and the colleagues reported that CD24+ liver tumor-initiating cells drive self-renewal and tumor initiation through STAT3-inducing NANOG expression, indicating that STAT3 signaling played important roles in the maintenance of CSCs in HCC." (PMID 28750679, 2017). "Notably, a larger tumor size of cervical neoplasia had a significant correlation with triple-positive API5+/FGF2+/NANOG+ expression." (PMID 28092370, 2017). "In BMSCC, NANOG is expressed in cells within the tumor nests and the peritumoral stroma." (PMID 28626726, 2017). "Inhibition of NANOG in GBM prevents tumor proliferation and invasion." (PMID 27148537, 2016). "SOX2 and NANOG were immunolocalized to the nuclei of tumor cells with high frequency." (PMID 26799577, 2016). "We envision that these small cells could be related to NANOG-positive tumor-like structures and oocyte-like cells in similar “chambers” found in sections of cancerous ovaries, which could support their stemness and pluripotency." (PMID 26940129, 2016). "To evaluate the role of NANOG on self-renewal and tumor growth independently, we generated stable rescue lines where NANOG expression was decreased in GLI1 overexpressing cells (GLI1+shNANOG) and corresponding empty vector (pCMV+pLKO.1) or GLI1 overexpression only controls (GLI1+pLKO.1)." (PMID 26189795, 2016). "Furthermore, CD133 depletion suppresses tumor cell proliferation, colony formation, and the expression of core stemness transcription factors including NANOG, octamer-binding transcription factor 4 (OCT4), SOX2, and c-MYC." (PMID 26539911, 2015).
tumor (continued). "Consistently, we found that the three main genes belonging to the stem cell regulatory network (POU5f, which encodes Oct4, NANOG and SOX2) were all significantly overexpressed in LMNA-KD-derived tumor spheres and even more so when the sphere cell population was cultured as adherent cells." (PMID 26439802, 2015). "Notably, treatment with rapamycin, a CSC targeting agent, attenuates stem-like phenotypes of the EML4-ALK+ cells, which increased capability of tumor formation and higher expression of stemness-associated molecules such as ALDH, NANOG, and OCT4." (PMID 26517679, 2015). "We subcutaneously injected 2 × 106NANOG1-knockout cells, NANOGP8-knockout cells, or parental cells into non-obese diabetic/severe combined immunodeficient (NOD-SCID) mice to determine whether NANOG depletion influences tumor development in vivo." (PMID 26087476, 2015). "Notably, NANOG was expressed in high quantities in all the tumor tissues studied, showing clear co-expression with DCLK1." (PMID 26622789, 2015). "Therefore, in NANOG-negative patients, CSCs expressing NANOG in early stage primary foci metastasize and form the secondary tumor." (PMID 24348816, 2014). "Importantly, our data indicated that the strong NANOG expression was associated with the initiation of a putative CSC population and promoted in vivo tumor metastasis." (PMID 24023739, 2013). "Oppositely, NANOG-knockdown cells generated tiny tumor nodules with lower levels of SOX2 and MUC1." (PMID 23662114, 2013). "The majority of OCT4+ cells in tumor and normal lactating tissues co-expressed NANOG." (PMID 23596564, 2013). "Similarly to OCT4, NANOG was also upregulated in the tumor tissues examined and showed a pattern of expression similar to OCT4." (PMID 23596564, 2013). "Here we present data that a variable fraction among the circulating tumour cells detected by the Maintrac® approach expresses mRNA of the stem cell gene NANOG and of the adhesion molecule vimentin and is capable of forming tumour spheres, a property ascribed to tumour-initiating cells (TICs)." (PMID 23983815, 2013). "Inhibiting NANOG gene expression may reduce tumor pathogenicity and stem cell characteristics in vitro, such as anchorage-dependent growth, while overexpression may enhance tumor cell stemness expression." (PMID 41264633, 2025). "Similarly, data from our analysis show that NANOG plays an agonist role in tumor growth." (PMID 41463190, 2025). "To verify whether monocyte- and macrophage-CM modulate the tumor plasticity of SCC cells, we analyzed the expression of genes associated with epithelial-mesenchymal transition (EPCAM, SOX2), stemness (NANOG, MYC, EZH2), and neuroendocrine differentiation (CHGA, AURKA, MYCN)." (PMID 41259557, 2025). "When the associations of the selected NANOG-regulated miRNAs with clinical parameters were analysed, we found that low expression of MIR9-2 was associated with higher tumour stages and presence of GCNIS, both indicating progression to an invasive tumour phenotype." (PMID 38693576, 2024). "Increasing evidence suggests that numerous m6A targets contribute to tumorigenesis, including Snail, CTNNB1, NANOG, APC, and genes associated with the Akt/mTOR pathway However, conflicting reports have indicated that METTL3 may function as a tumor suppressor in certain tumor types." (PMID 38012755, 2023). "We then questioned whether TRPV1 potentiates the refractory phenotypes of NANOG+ tumor cells." (PMID 37165076, 2023). "Moreover, these drugs may also have the possibility to up-regulate genes favored for tumor progression particularly for the NANOG." (PMID 37894463, 2023). "Furthermore, TRRAP knockdown significantly reduced tumor growth in a murine xenograft transplantation model, which could be reversed by NANOG overexpression." (PMID 37047234, 2023).
tumor (continued). "In light of this, our data propose that increase in CD59 might result from immune selection of NANOG+ CTL-refractory tumor cells, but it may not be its cause, at least during CTL-mediated immune selection." (PMID 35606403, 2022). "Given that OCT4, SOX2 and NANOG are crucial to maintain stemness, we need a greater knowledge of the mechanisms that regulate the expression of these factors to design new therapeutic interventions that can eventually overcome issues such as chemotherapy resistance, tumor recurrence, and metastasis." (PMID 36118530, 2022). "As the NANOG/HDAC1 axis has been implicated as a central channel in the development of resistance to CTL-based immunotherapies, we believe that HDAC1 inhibition may be an effective strategy to control ICB therapy–refractory tumor cells with elevated expression of NANOG." (PMID 35104240, 2022). "Noteworthy, the CD8+/FOXP3+ TILs ratios in both tumor nests and stroma were consistently higher in tumors harboring negative expressions of NANOG and SOX2; however, significant associations were only reached between the tumoral CD8+/FOXP3+ ratio and both SOX2 and NANOG." (PMID 34201050, 2021). "Therefore, we next tested whether human NANOG could regulate migration of tumor cells through CXCR4." (PMID 34638956, 2021). "Taken together, our study identifies a novel mechanism of TGF-β signaling in tumorigenesis through downregulating the expression of SPOP, a potential tumor suppressor, which may lead to the upregulation of NANOG as we previously reported and consequently enhanced stemness in PCa." (PMID 32364525, 2020). "Therefore, since the clinical relevance of NANOG expression is influenced by some clinicopathological characteristics, differences in tumor localization and N classification of the patients included could explain the discrepancies between reported studies." (PMID 32635524, 2020). "Since OIP5-AS1 is expressed at high level in undifferentiated tumor cells, we asked the question whether the promoter of OIP5-AS1 gene has possible binding motifs for stemness associated TFs (Yamanaka factors) MYC, KLF4, OCT4, SOX2, and NANOG." (PMID 29728583, 2018). "Moreover, tumor-like structures and even primitive oocyte-like cells, positive for NANOG, were found in similar “chambers”, indicating that they might develop from small putative stem cells expressing NANOG, within these “chambers”." (PMID 26940129, 2016). "The presence of OCT4+/NANOG+ cells in the mammary stroma both in the normal lactating and the tumor tissues examined further supports this theory, suggesting that self-renewal and differentiation in the mammary stroma may be controlled by the same TF network that regulates the mammary epithelium." (PMID 23596564, 2013). "Therefore, we hypothesize that demethylation of NANOG occurs during tumor development and the corresponding expression of NANOG provides tumor cells with metastatic CSC properties." (PMID 24023739, 2013). "Knocking out PGC specification inducers (ACVR1, SMAD5, PRDM1, or SOX17) or fate-maintaining genes (NANOG or DDX4) suppressed both SPLC and tumor initiation." (PMID 42291258, 2026). "In the later stage, the expression and function of these tumor suppressor genes are diminished and endogenous expression of stemness genes such as OCT4, SOX2, NANOG, or other pluripotent genes is induced, leading to complete reprogramming into full-iPSCs." (PMID 40689085, 2025). "DUSP9‐overexpressing tumours showed higher levels of DUSP9, SCD, NANOG and Ki67, whereas DUSP9‐knockdown tumours displayed reduced expression of these markers." (PMID 41383134, 2025). "BIN1 overexpression correlated with reduced expression of key stemness and EMT markers, including Myc, ALDH1, OCT4, EPCAM, KLF4, NANOG, SOX2, and decreased tumor sphere-formation capabilities, suggesting EMT inhibition." (PMID 40016843, 2025).
tumor (continued). "In particular, Wi-N and TEG caused a stronger reduction in the self-renewal capability of CSCs than Wi-A, as evidenced by a tumor spheroid formation assay and analyses of stemness-related genes (ALDH1, CD44, NANOG, CD133, SOX2)." (PMID 39859209, 2025). "In this context, understanding the prognostic roles of pluripotency transcription factors, particularly SOX2 and NANOG, in re-OSCC is critical, given their established links to CSC biology and tumor progression." (PMID 40227667, 2025). "These cells exhibited enhanced stem-like properties, including upregulation of NANOG expression, expansion of the CD24− cell population, and increased tumor formation." (PMID 40703657, 2025). "Abnormal expression of transcription factors SOX2 (SRY-related HMG-box gene 2), NANOG, and OCT4 is known to have different functions in tumor initiation and metastasis." (PMID 40227667, 2025). "NANOG interacts with a variety of druggable pathways, including HA-CD44, STAT3, PKC, and metabolic pathways, which all contribute to drug resistance and tumor progression." (PMID 40227667, 2025). "By categorizing the perivascular region into two distinct zones based on their proximity to tumor cells—far and close—it was found that stemness markers (CD15, CD133, SOX2, NES, and NANOG) exhibited higher expression levels in regions closer to blood vessels." (PMID 41041071, 2025). "Low levels of KLF4, c-MYC, and NANOG and high expressions of SOX2 and OCT4 in tumor tissue correlated with poor overall survival (OS) and disease-free survival (DFS), respectively." (PMID 41463190, 2025). "Inflammatory cytokines and tumor-derived mediators released into the bloodstream interact with PBMCs, triggering intracellular signaling pathways that upregulate CK19, NANOG, and INS genes." (PMID 40699634, 2025). "Our results also revealed that SOX2 and NANOG were highly expressed in ESCC, and their expressions were correlated with lymph node metastasis and the late pathological stage of the tumor." (PMID 40626009, 2025). "SCs, especially those that emerge following therapy or in specific tumor microenvironments, can upregulate core pluripotency factors including SOX2, OCT4, and NANOG." (PMID 40703657, 2025). "We showed the expression levels of NANOG, BMI1, and SOX2, which are the pluripotency transcription factors involved in the regulation of CSCs, strongly grew along with advanced pathological tumor grade, whereas OCT4 was unchanged." (PMID 40016182, 2025). "The collaborative actions of NANOG, OCT4, and SOX2 contribute to the survival and persistence of CSCs, making them key factors in tumor recurrence and therapeutic resistance." (PMID 40759634, 2025). "Research indicates that miR-145 exerts anti-stemness and tumor inhibitory effects by directly targeting OCT4, NANOG, SOX2 and KLF4, conversely, these pluripotent TFs can also induce or inhibit the transcription of diverse miRNAs." (PMID 38561775, 2024). "Meanwhile, co-culture with NK cells upregulated the expression of KI67, a sign of proliferation for tumor malignancy, and stemness markers CD90, CD44, LGR5, and NANOG in CRC cells." (PMID 38543173, 2024). "The 3D osteosarcoma cells were successfully enriched with CSCs, in order to reproduce the CSC-tumor niche behavior, as evidenced by the increased mRNA expression level of stem-related genes, such as OCT-4, SOX-2 and NANOG." (PMID 38791452, 2024). "Meanwhile, NANOG, OCT4 and ALDH1 mRNA and Ki67 protein levels were dropped in tumor tissues of the TSP50 knockdown group." (PMID 39030572, 2024). "To validate the changes in stemness of the tumor cells processed by the MCTS model, we evaluated the changes in transcription factors (OCT4, NANOG, and SOX2) using qRT-PCR." (PMID 38254728, 2024). "Intriguingly, following NK cell killing, the CD133 level of surviving tumor cells was dramatically increased from 20% to 80%, accompanied by upregulation of SOX2, OCT4, and NANOG stem cell marker expression." (PMID 38494433, 2024).